TBC1D24 (TBC1 domain family member 24)
Description:
May act as a GTPase-activating protein for Rab family protein(s). Involved in neuronal projection development, probably through negative modulation of ARF6 function. Required for the maintenance of postsynaptic neuron dendritic spines in the adult by suppressing ARF6 activity. Involved in the regulation of synaptic vesicle trafficking. Promotes axonal outgrowth and membrane trafficking at the growth cone (By similarity). Positively regulates radial migration and morphological maturation of pyramidal neurons during cortical development by preventing ARF6 activation (By similarity). In one study, has been shown to inhibit the activity of the vacuolar-type ATPase (V-ATPase) by inducing disassembly of the V-ATPase complex. In another study, has been shown to positively regulate V-ATPase assembly in neurons which promotes acidification of lysosomes and synaptic vesicles (By similarity). This supports neuronal autophagy and also regulates synaptic vesicle reacidification and the maintenance of the synaptic vesicle reserve pool (By similarity). Protects neuronal cells against oxidative stress. Involved in the maintainenance of endosomal-mediated vesicle recycling and sustained exocytosis of hair cell ribbon synapses (By similarity). Facilitates formation of tubular recycling endosomes which promotes recycling of clathrin-independent endocytosis cargo proteins back to the plasma membrane.
Synonyms: KIAA1171; TLDC6; DFNA65; DEE16; DFNB86; DOORS; EIEE16; EIM; EPRPDC; FIME
Tractability: Antibody: UniProt places it where antibodies can reach, with high confidence; its Gene Ontology location is reachable by antibodies, with high confidence; the Human Protein Atlas places it where antibodies can reach. PROTAC: ubiquitination databases record sites on it; its protein half-life has been measured.
Gene: Protein-coding gene on chromosome 16 (2,475,051 to 2,509,671, forward strand). Ensembl gene ENSG00000162065.
Subcellular location: Cell membrane; Cytoplasm; Cytoplasmic vesicle membrane; Presynapse; Postsynapse; Cell projection, neuron projection; Cell projection, dendrite; Perikaryon; Cell projection, growth cone; Cytoplasmic vesicle, clathrin- coated vesicle
Subcellular location (Human Protein Atlas): Cell Junctions; Plasma membrane
Pathways (Reactome):
Vesicle-mediated transport: TBC/RABGAPs
Gene Ontology:
Molecular function: protein binding
Biological process: cellular response to oxidative stress; neuron projection development; regulation of cilium assembly; positive regulation of dendrite morphogenesis; positive regulation of excitatory postsynaptic potential; positive regulation of neuron migration
Cellular component: cell junction; cytoplasm; plasma membrane; presynapse; cytoplasmic vesicle membrane; neuromuscular junction; terminal bouton; clathrin-coated vesicle; dendrite; growth cone; neuron projection; perikaryon; postsynapse
Genetic constraint (gnomAD): Loss-of-function variants: 47 observed, 49.37 expected, observed/expected ratio (o/e) 0.95, 90% interval 0.75 to 1.21. The upper end of that interval is the gene's LOEUF score, 1.21, which puts it in group 5 of 6, group 1 being the genes least tolerant of losing a copy. Missense variants: 688 observed, 771.46 expected, observed/expected ratio (o/e) 0.89, 90% interval 0.84 to 0.95. Synonymous variants: 324 observed, 334.81 expected, observed/expected ratio (o/e) 0.97, 90% interval 0.88 to 1.06.
Gene-disease validity (ClinGen):
ClinGen rates the evidence that TBC1D24 causes each of these diseases.
DOORS syndrome (autosomal recessive): Definitive. DOORS syndrome (also known as DOOR syndrome) is a multiple congenital anomalies-intellectual disability syndrome characterized by sensorineural hearing loss (deafness), onychodystrophy, osteodystrophy, mild to profound intellectual disability, and seizures.
nonsyndromic genetic hearing loss (autosomal dominant): Limited. A disease characterized by hearing loss that is not part of a larger syndrome.
Homologues: Orthologues: chimpanzee TBC1D24 (100% identical), macaque TBC1D24 (99% identical), rat Tbc1d24 (94% identical), guinea pig TBC1D24 (93% identical), dog TBC1D24 (93% identical), mouse Tbc1d24 (93% identical), pig TBC1D24 (91% identical), rabbit TBC1D24 (89% identical), tropical clawed frog tbc1d24 (69% identical), zebrafish tbc1d24 (61% identical), Drosophila melanogaster sky (31% identical), Caenorhabditis elegans tbc-7 (25% identical).
Diseases named in the same sentence as TBC1D24 in open-access papers:
TBC1D24 is named in the same sentence as 72 diseases in open-access papers, as found by Europe PMC text mining. Sharing a sentence is not in itself a finding about the gene and the disease. The quoted sentences say what the papers report.
epilepsy (25 papers, 2014 to 2025). A brain disorder characterized by episodes of abnormally increased neuronal discharge resulting in transient episodes of sensory or motor neurological dysfunction, or psychic dysfunction. "Later, more than 50 mutations in TBC1D24 have been associated with various types of drug-resistant epilepsy, intellectual disability, and DOORS (deafness, onychodystrophy, osteodystrophy, mental retardation, and seizures) syndrome." (PMID 37773136, 2023). "Mutations in the TBC1D24 presynaptic protein are associated with a neurological spectrum of epilepsy, chronic encephalopathy, DOORS (deafness, onychodystrophy, osteodystrophy, mental retardation and seizures), hearing loss, and myoclonus." (PMID 37008993, 2023). "The disorders associated with TBC1D24 are characterized by some features which were described as distinct, recognized phenotypes originally, including deafness, epilepsy, intellectual disability, and osteodystrophy." (PMID 36570450, 2022). "It was identified as a potential drug target for Alzheimer’s disease, Down syndrome, and TBC1D24-associated epilepsy, while also loss-of-function mutations in Synj1 are associated with epilepsy and Parkinson’s disease." (PMID 33349335, 2020). "Apart from being a potential drug target for Alzheimer’s disease, Down syndrome, and TBC1D24-linked epilepsy, loss-of-function mutations in Synj1 also lead to disease, including epilepsy and Parkinson’s disease." (PMID 33349335, 2020). "Since perturbed excitatory PSD signaling is linked to both epilepsy and ID, we aim to explore the postsynaptic function of TBC1D24." (PMID 32004315, 2020). "The importance of TBC1D24 in normal brain function was first demonstrated by the identification of mutations in patients with various forms of epilepsy." (PMID 28707022, 2017). "We evaluated the types of epilepsy seen with a wide mutational spectrum in TBC1D24, using new data from 11 previously unreported and 37 published patients." (PMID 27281533, 2016). "TBC1D24 is associated with an even broader phenotypic spectrum, including a number of conditions other than epilepsy alone (i.e., DOORS syndrome and nonsyndromic deafness) and involving multiple organs other than the brain." (PMID 27281533, 2016). "TBC1 domain family member 24 (TBC1D24) is an Arf6-interacting protein, and mutations in the TBC1D24 gene are associated with cortical malformation, intellectual disability, and epilepsy." (PMID 26733777, 2015). "A mutation in TBC1D24 was the first genetic cause of human epilepsy found." (PMID 37773136, 2023). "Epilepsy phenotypes associated with pathogenic variants of TBC1D24 include familial infantile myoclonic epilepsy, epilepsy of infancy with migrating focal seizures (EIMFS) and DOORS (deafness, onychodystrophy, osteodystrophy, intellectual disabilities, and seizures) syndrome." (PMID 35350397, 2022). "Diverse mutations on the human TBC1D24 gene are strongly associated with epilepsy and ID." (PMID 32004315, 2020). "Although many patients carrying TBC1D24 gene mutations show early-onset epilepsy and developmental delay, our findings on mice with acute hippocampal TBC1D24 knockdown in vivo indicate that adult-onset depletion of TBC1D24 can produce detrimental effect on cognitive function and behaviors." (PMID 32004315, 2020). "TBC1D24 mutation-related epileptic syndrome includes a wide spectrum of epilepsies." (PMID 29416524, 2018). "Finally, we assessed mutations in the TLDc domain relevant to epilepsy by testing a Tbc1d24 A515V mutant (equivalent to human A509V) as well as a truncation mutant (Cys156X) to mirror a TBC1D24 frameshift mutation that results in the loss of the TLDc domain." (PMID 26668325, 2016). "In the homozygous mutant mice, substantial loss of TBC1D24 expression during early development leads to increased neuronal excitability, spontaneous seizure and postnatal death, which agrees with the reported cases of epilepsy in most individuals harboring TBC1D24 gene mutations." (PMID 32004315, 2020).
epilepsy (continued). "While functional studies have focused on the role of TBC1D24 at the synapse, it must also be considered that TBC1D24 confers neuronal resistance against OS via its TLDc domain; for example, epilepsy-associated mutations appear to be detrimental to OS resistance in neurons." (PMID 28707022, 2017). "Furthermore, with an increasing number of pathogenic mutations leading to epilepsy and hearing loss being discovered in the TLDc protein TBC1D24, understanding the function of this family has important implications for a range of inherited neurological diseases." (PMID 28707022, 2017). "We also observed that epilepsy-associated genes PDCC10, PHGDH, PSAT1, and TBC1D24 showed higher expression levels in SOZ compared with PZ." (PMID 39541170, 2025). "TBC1D24, a member of the same protein family as TBC1D8, regulates neuronal migration and its epilepsy-related mutation is in the Rab-GAP TBC domain, which is the same domain containing the mutation evaluated in our study." (PMID 33584793, 2020). "Two high-ranking DMPs lie within the TBC1D24 and FBOX9 genes respectively, and both have previously been associated with epilepsy." (PMID 29484035, 2018). "By compiling the epilepsy and DOORS-associated TBC1D24 mutations detected to date with their corresponding clinical features, there is some evidence that the more severe clinical phenotypes are associated with nonsense, frameshift or splice-site mutations." (PMID 28707022, 2017). "In TBC1D24-associated disorders, including deafness, onychodystrophy, osteodystrophy, mental retardation, and seizures (DOORS) syndrome, a wide spectrum of epilepsies have been reported." (PMID 27281533, 2016). "We collected a modest number of patients in absolute terms, but TBC1D24-related epilepsy is rare and we report a relatively large series compared with other rare genetic neurologic conditions with epilepsy." (PMID 27281533, 2016). "We used the following search terms: “DOOR syndrome”, “DOORS syndrome”, “deafness and onychodystrophy”, “TBC1D24”, “2-oxoglutaric aciduria”, “2-oxoglutarate”, “epilepsy”, and “exome sequencing”." (PMID 24291220, 2014). "Interestingly, despite the presence of the epilepsy gene TBC1D24 in the genomic deletion, ATP6V0C haploinsufficiency was proposed as the primary contributor to the clinical features of the 16p13.3 microdeletion syndrome." (PMID 39273013, 2024). "Human genetic studies have linked numerous mutations on TBC1D24, a gene whose function is not well-defined, to epilepsy and intellectual disability." (PMID 32004315, 2020). "Epilepsy is characterised by spontaneous neuronal activity that often arises from defects in neuronal development, migration or synaptic transmission; therefore, the role of TBC1D24 in these specific processes has been assessed both in vitro and in vivo." (PMID 28707022, 2017). "For example, TBC1D24, may only be available on an epilepsy panel." (PMID 34177764, 2021). "Wide spectrum of missense and frameshift mutations have been identified on the TBC1D24 gene in about 50 patients with syndromic ID and the deafness, onychodystrophy, osteodystrophy, mental retardation, and seizures (DOORS) syndrome, both of which are associated with different types of epilepsy." (PMID 32004315, 2020). "Further evidence for the significance of TBC1D24 haploinsufficiency is provided by the very recent description of heterozygous microdeletions spanning TBC1D24 and a small number of adjacent genes; these individuals display epilepsy, microcephaly and developmental delay." (PMID 30335140, 2019).
deafness (20 papers, 2014 to 2024). An inherited or acquired condition characterized by the complete loss of the ability to hear from one or both ears. "We conducted a thorough investigation of patients with non-syndromic deafness caused by TBC1D24 gene mutation and compared the HPT of low, mid, and high frequencies." (PMID 38413761, 2024). "Multiple studies have documented both dominant and recessive non-syndromic deafness, as well as syndromic deafness, resulting from mutations in the TBC1D24 gene." (PMID 38413761, 2024). "We engineered a mouse model of the human TBC1D24 dominant p.Ser178Leu allele associated with deafness DFNA65." (PMID 32987832, 2020). "DOORS [deafness, onychodystrophy, osteodystrophy, intellectual disability (mental retardation), and seizures] syndrome can be caused by mutations in the TBC1D24 and ATP6V1B2 genes, both of which are involved in endolysosomal function." (PMID 32849222, 2020). "Pathogenic variants of human TBC1D24 are associated with a spectrum of skeletal and neurological disorders including deafness, seizures, onychodystrophy, osteodystrophy and intellectual disability." (PMID 32987832, 2020). "Twenty-eight pathogenic variants of TBC1D24 are associated with syndromic deafness, including a novel splice-site variant c.965 + 1G > A which is segregating in a Pakistani family reported in this study." (PMID 32987832, 2020). "Nevertheless, a comprehensive understanding as to how human TBC1D24 variants cause DFNB86 deafness, as well as a panoply of other allele-associated abnormalities remains to be explored." (PMID 32987832, 2020). "Human TBC1D24 has an essential function required for normal hearing, since several different human variants of TBC1D24 are associated with non-syndromic deafness or syndromic deafness." (PMID 32987832, 2020). "One of the recurrent clinical features of individuals with TBC1D24 mutations is deafness; therefore, we also analysed auditory function and the ultrastructure of the inner ear in Tbc1d24tm1b mice." (PMID 30335140, 2019). "In this study, we used NGS technology, which led to the identification of novel alleles in SLC26A4, MYO15A, OTOG, LOXHD1, and TBC1D24 that are associated with deafness." (PMID 30139988, 2018). "Of note, some variants in TBC1D24 are associated with deafness, onychodystrophy, osteodystrophy, mental retardation and seizures (DOORS)." (PMID 30139988, 2018). "Heterozygous carriers of truncating TBC1D24 gene mutations in a certain family exhibit a normal clinical phenotype, suggesting that the TBC1D24 gene mutation p.Ser178Leu associated with non-syndromic dominant deafness is likely a gain-of-function mutation." (PMID 38413761, 2024). "There is decisive data supporting an association of deafness with variants of human TBC1D24." (PMID 32987832, 2020). "At present, there are 96 variants of TBC1D24, including missense, nonsense, splice site, small indels and gross insertion and deletions that are associated with non-syndromic and syndromic forms of deafness as well as seizures." (PMID 32987832, 2020). "Thirty-five pathogenic variants of human TBC1D24 associated with deafness have been reported." (PMID 32987832, 2020). "Moreover, ARF6-dependent trafficking has been recently implicated in inner-ear hair cell function, suggesting that membrane trafficking defects in hair cells can be implicated in TBC1D24-associated deafness." (PMID 30335140, 2019). "However, there might be other explanations as to why particular homozygous or compound heterozygous variants of TBC1D24 are deafness-causing in humans, while the very same variants in mouse Tbc1d24 did not affect hearing." (PMID 32987832, 2020). "A Mutation in the gene TBC1 Domain Family Member 24 (TBC1D24), encoding for a GTPase activating the proteins Rab5 and Rab35, involved in endosome to lysosome trafficking as a mechanism for degrading synaptic vesicles associated proteins, has been shown to cause severe neurodegeneration and deafness." (PMID 29760588, 2018).
deafness (continued). "Bakhchane and colleagues reported that individuals with TBC1D24 compound heterozygous p.Arg214His/p.Val445Glyfs*33 and p.Arg214His/p.Glu153Lys exhibited non-syndromic deafness DFNB86." (PMID 32987832, 2020). "To evaluate the auditory function of a mouse model of human TBC1D24 syndromic deafness, we tested hearing by ABR analyses using compound heterozygous p.Ser324Thrfs*3/p.His336Glnfs*12 mice." (PMID 32987832, 2020). "Variants of TBC1D24 are also associated with syndromic hearing loss, which includes hearing loss with seizures, or a multisystem disorder named DOORS (Deafness, Onychodystrophy, Osteodystrophy, mental Retardation and Seizures)." (PMID 32987832, 2020). "Following the first report of two recessive variants of human TBC1D24 associated with DFNB86, six additional pathogenic variants of TBC1D24 have been reported to associate with non-syndromic deafness." (PMID 32987832, 2020). "In summary, we report a novel pathogenic splice-site variant of TBC1D24 segregating in a Pakistani family, and describe several mouse models of human TBC1D24 associated with DFNB86, DFNA65 and syndromic deafness." (PMID 32987832, 2020). "The analysis of NGS data led to the identification of five novel variants in the known deafness genes MYO15A, LOXHD1, TBC1D24, and OTOG, all of which were associated with pathogenicity, and categorized according to the ACMG guidelines." (PMID 30139988, 2018). "Homozygous or compound heterozygous TBC1D24 mutations cause a broad spectrum of neurological disorders, including several epileptic disorders, DOORS (deafness, onychodystrophy, osteodystrophy and mental retardation) syndrome or syndromic and non-syndromic deafness." (PMID 32443735, 2020). "The genotype-phenotype relationship of human TBC1D24 variants associated with seizures are recapitulated in variants of mouse Tbc1d24, unlike deafness." (PMID 32987832, 2020). "Mutations in the TBC1D24 gene are responsible for four neurological presentations: infantile epileptic encephalopathy, infantile myoclonic epilepsy, DOORS (deafness, onychodystrophy, osteodystrophy, mental retardation and seizures) and NSHL (non-syndromic hearing loss)." (PMID 26371875, 2015). "Of the 18 individuals with DOORS syndrome from 17 families without TBC1D24 mutations, eight did not have seizures and three did not have deafness." (PMID 24291220, 2014). "However, functions of TBC1D24 in the inner ear and the pathophysiology of TBC1D24-related deafness are unknown." (PMID 32987832, 2020). "Thus, individuals with DOORS syndrome without deafness and seizures but with the other features should still be screened for TBC1D24 mutations." (PMID 24291220, 2014). "The clinical heterogeneity of affected members of family PKDF1429 suggests that the TBC1D24 genotype alone does not unequivocally dictate the phenotype, i.e., either non-syndromic deafness or the combination of deafness and seizures." (PMID 32987832, 2020).